LAMA3 (laminin subunit alpha 3)
Diseases named in the same sentence as LAMA3 in open-access papers (continued):
Sharing a sentence is not in itself a finding about the gene and the disease.
tumor (69 papers, 2007 to 2025). "LAMA3 is a key component of laminin-332 in the basement membrane, and its overexpression in the tumor microenvironment has been implicated in cancer cell infiltration and metastasis." (PMID 41264049, 2025). "Increased LAMA3 expression correlated with large tumor size (P = 0.007), and the degree of LAMA3 expression was associated with different TNM stages (P = 0.002)." (PMID 38452390, 2024). "Through the synergistic action of AP-1 binding sites, the epithelial enhancer mediates the production of laminin subunit alpha 3 (LAMA3), which is associated with tumor progression." (PMID 36245988, 2022). "Lama3 mutations correlated with tumour grade (p = 0.00233), total immune infiltrate (CD45+, p = 0.029824), exofitic tumour growth (p = 0.05172) and tumour invasiveness (p = 0.02748)." (PMID 33168804, 2020). "We have linked Lama3 mutations to tumour invasiveness and Notch1 mutations to an increased immune cell infiltrate, and explored the clonal architecture of individual tumours." (PMID 33168804, 2020). "The analysis identified a splice variant of LAMA3 (Laminin α 3), LAMA3-A, known to be involved in tumour cell invasion and progression." (PMID 19936049, 2009). "However, our analysis of clinical data revealed that high LAMA3 expression was associated with larger tumor size, advanced TNM stage, and liver metastasis." (PMID 38452390, 2024). "The loss of Laminin-α3 (Lama3) in higher-grade tumours (moderate dysplasia to invasive SCC) could be used as a marker to predict metastatic behaviour." (PMID 33168804, 2020). "Increased expression of LAMA3, a subunit of laminin 5, is associated with response to PG-11047 suggesting the possibility that tumours responding to the drug also may experience reduced EMT." (PMID 20003408, 2009). "Previous studies indicate that aberrant expression of LAMA3 can influence tumor behavior through activation of signaling pathways such as PI3K/AKT and MAPK, thereby modulating cell survival, proliferation, and migration." (PMID 41264049, 2025). "LAMA3, LAMB3 and LAMC2 genes encode for laminin-332, which is related to tumor invasiveness and metastasis and is considered a factor of poor prognosis." (PMID 38473784, 2024). "LAMA3 expression in tumor tissues from patients with PDAC and liver metastasis was significantly higher than in those without liver metastasis (P = 0.005)." (PMID 38452390, 2024). "This signature consists of 5 genes (HOTAIR, PLK1, LAMA3, EDA2R, and IKZF3) that are closely linked to tumor development." (PMID 37904416, 2023). "The largest expression differences between tumour and normal samples were observed for LAMA3 (mean fold change; mfc = 21.7, p = 2.1 × 10−61), LAMB3 (mfc = 55.3, p = 7.9 × 10−60), and LAMC2 (mfc = 51.0, p = 3.8 × 10−61) transcripts." (PMID 37779898, 2023). "From the figure, except for LAMA3, the methylated expression level in tumor tissues was significantly higher than that in normal tissue." (PMID 37563710, 2023). "Abnormal LAMA3 levels affect the synthesis of laminin, hinder the formation of basement membrane, and promote tumor cell invasion and metastasis." (PMID 33992120, 2021). "As a laminin coding gene, LAMA3 has been proved to be involved in the occurrence and development of tumors, promote the proliferation of tumor cells, and affect the invasion and metastasis of tumors." (PMID 33992120, 2021).
tumor (continued). "Limited analysis of the LAMA3 gene revealed that there is loss of LAMA3 exon 1 in the blocks without HPV E5-LAMA3 integration, but exon 2 is present in all three tumor areas." (PMID 32954225, 2020). "In PDAC tumor tissues, the expression of LAMA3 and LAMC2 are upregulated with a favorable ability of distinguishing between PDAC and non-tumor tissues, which is of a prognostic value for PDAC patients." (PMID 31182680, 2019). "The majority of genes in the PAC-5 signature (LAMA3, E2F7, SLC12A2, and LRIG1) have been reported to be associated with tumour progression in various types of cancer." (PMID 31703415, 2019). "Two key differentially expressed subunits (LAMA3 and LAMC2) that are associated with prognosis of PDAC patients were found to show a potential for distinguishing between PDAC and non-tumor tissues." (PMID 31182680, 2019). "The interactions between LAMA3 subunit of laminin 332 with α6β4 integrin and syndecan 1 leads to the activation of protein kinase C (PKC) pathway which causes tumor cell migration and invasion." (PMID 31409848, 2019). "LM-332 (encoded by LAMA3, LAMB3, and LAMC2) has been linked to tumor invasiveness in various types of cancer." (PMID 29426928, 2018). "In our exon array analysis, manual review of LAMA3 gene plots demonstrated 23 of 44 tumor samples with a splicing pattern predominantly expressing the shorter LAMA3A isoforms." (PMID 24675808, 2014). "Laminin 3 (LAMA3) forms the subunit of laminin-332, an extracellular glycoprotein, known to be important in cell migration and tumour invasion." (PMID 19936049, 2009). "In addition, LAMA3 and LAMB3, encoding the α3 and β3 chains of Laminin‐332, were also highly expressed in the tumor basal stem‐like cell region compared to normal epithelial areas." (PMID 40470730, 2025). "Our results also showed that LAMA3 expression was associated with TNM stage, suggesting that it could contribute to assessing tumor aggressiveness and prognosis." (PMID 41264049, 2025). "Importantly, LAMA3 has been proposed as a potential therapeutic target in other malignancies, where inhibition of its expression or function reduced tumor invasion and metastasis." (PMID 41264049, 2025). "Future studies should investigate whether LAMA3 can be detected in serum or other body fluids, which would allow for less invasive and more dynamic monitoring of tumor biology." (PMID 41264049, 2025). "High LAMA3 expression correlated with large tumor size and TNM stage." (PMID 38452390, 2024). "In addition, LAMA3 expression was higher in tumor tissue from patients with PDAC and liver metastases than those without liver metastases (P = 0.005)." (PMID 38452390, 2024). "Laminin subunit alpha 3 (LAMA3) is known to modulate tumor progression." (PMID 38452390, 2024). "Studies indicated that LAMA3 is a promising target for cancer therapy since it may accelerate the growth and invasion of tumour cells." (PMID 37745080, 2023). "Patients with the upper third LAMA3 (p = 0.01), LAMB3 (p = 0.01) and LAMC2 (p = 0.01) transcript abundance were each associated with a higher histological grade, while high LAMA3 (p = 0.001) and LAMC2 (p = 0.01) were associated with the residual tumour stage." (PMID 37779898, 2023). "Cell adhesion and cell migration are the critical steps in the invasive process of metastatic tumor cells, we assessed whether LAMA3 silencing dysregulated the adhesive and motility abilities of CCA cells." (PMID 38114514, 2023). "Seven ECMGs (i.e. LAMB3, LAMA3, ITGB6, ITGB4, ITGA2, LAMC2, and COL11A1) were identified to be hub genes of PAAD, which were obviously up-regulated in PAAD and considerably linked to tumor stage as well as prognosis." (PMID 36311789, 2022). "Similarly, LAMA3 was increased in tumor tissues and correlated with the poor prognosis of PDAC patients 39, while SERPINE1 promoted PC cell proliferation and invasion." (PMID 34326696, 2021).
tumor (continued). "In the analysis between the tumour tissues, mRNAs of LAMA3, E2F7, and IFI44 were more expressed in the tissues of the high-risk group than in those of low-risk group, whereas the expression levels of IFI44 and LRIG1 were lower in the high-risk group than in low-risk group." (PMID 31703415, 2019). "The expression of LAMA3 and LAMC2 was found to be upregulated in PDAC tumor tissues in the 9 datasets, with a favorable diagnostic ability for distinguishing between PDAC and non-tumor tissues." (PMID 31182680, 2019). "In addition, molecular imaging approaches targeting LAMA3 may provide new opportunities for real-time assessment of tumor aggressiveness and therapeutic response." (PMID 41264049, 2025). "Similarly, several genes encoding proteins involved in tumor shedding, adhesion and migration, such as collagens (COL4A5, COL4A6), integrins (ITGB4) and laminins (LAMA3), were overexpressed and positively associated with pathogenic bacteria in OSCC tumor microenvironment." (PMID 38589501, 2024). "We cannot infer from these data alone whether the combinatorial effect reflects the expression of the LM332 protein driving tumour progression or are a consequence of shared dysregulation, but these findings suggest that adding LAMA3 to existing biomarkers may improve their functionality." (PMID 37779898, 2023). "Moreover, it is plausible that the role of LAMA3 changes dynamically with tumor progression: in early stages, it may promote local expansion via cell adhesion and tissue remodeling, whereas in advanced stages, it may facilitate distant metastasis and PNI through ECM degradation and remodeling." (PMID 41264049, 2025). "Univariate analysis suggested that tumor size, TNM stage, liver metastasis, and LAMA3 expression had a significant prognostic influence on OS." (PMID 38452390, 2024). "An examination of mRNA levels within the TCGA-GTEx cohort demonstrated a notable increase in KLK10, LAMA3, MET, KRT7, and SFTA2, alongside a decrease in MT1X in tumor samples compared to their normal counterparts." (PMID 38893622, 2024). "These analyses identified that LAMA3, LAMB3, and LAMC2 expression levels are increased at the mRNA and protein levels in PAAD tumours with evidence of co-regulation." (PMID 37779898, 2023). "The findings presented here show that LAMA3, LAMB3, and LAMC2 are frequently upregulated at the gene and protein levels in PAAD tumours compared with controls and that these increases are related to worse survival outcomes." (PMID 37779898, 2023). "Promoter methylation was lower in PAAD than normal pancreatic tissues for all three genes (LAMA3 normal β:0.43, tumour β:0.34, p = 2.8 × 10−9; LAMB3 normal β:0.65, tumour β:0.53, p = 8.6 × 10−7; and LAMC2 normal β:0.44, tumour β:0.38, p = 0.04)." (PMID 37779898, 2023). "The expressions in the tumor tissues also generally correlated with MIR31HG levels (r = 0.523, r = 0.367, and r = 0.287 for FLNB, LAMA3, and MMP1, respectively)." (PMID 36980216, 2023). "While functional data suggest that LaNt α31 could be capable of influencing tumour progression, further rationale for investigating this protein in tumour microenvironment comes from studies of the other, more comprehensively studied, products of the LAMA3 gene." (PMID 35231053, 2022). "The results showed that the expression levels of ITGA2, ITGB6, LAMA3, LAMB3, and LAMC2 are significantly correlated with the tumor stage of PAAD patients, while the expression levels of COL1A2 are not correlated with the tumor stage of PAAD patients." (PMID 35899199, 2022). "There is evidence for recurrent DNA methylation of LAMA3 and SERPINB5 genes on the remaining copy of chromosome 18, which suggests a “second hit” common to tumor suppressor genes." (PMID 34680217, 2021). "LAMC2 together with laminin subunit beta-3 (LAMB3) and laminin subunit alpha-3 (LAMA3) constitutes laminin-332, which is secreted by epithelial tumor cells, thereby regulating cancer invasion." (PMID 34612783, 2021).
tumor (continued). "The ROC analysis of LAMA3, LAMC2 and their combined expression in PDAC sets indicate that both genes display high accuracy in distinguishing between tumor and non-tumor tissues (the AUCs of the ROC curves were >0.70)." (PMID 31182680, 2019). "The results show that LAMA3 and LAMC2 expression is significantly upregulated in PDAC tumor tissues in most studies." (PMID 31182680, 2019). "Experimental validation showed that MLF1IP, LAMA3 and LAMB3 were progressively increased from tumor initiation to progression." (PMID 30598639, 2018). "Several studies showed Laminin 332 (LAMA3, LAMB3 and LAMC2) to be highly expressed in HNSCC and foster tumor invasiveness, an effect that is reversed when the laminins are repressed by microRNA‐29s." (PMID 27596625, 2016). "The expression level of miR-218 was significantly downregulated in tumor tissues compared with adjacent normal tissues (p = 0.039), whereas LAMA3, LAMB3 and LAMC2 were upregulated in tumor tissues (P = 0.018, p = 0.0029 and p = 0.0009, respectively)." (PMID 23159910, 2012). "Mechanistically, LAMA3 may facilitate cancer cell migration and invasion by altering extracellular matrix (ECM) composition and enhancing tumor–nerve interactions." (PMID 41264049, 2025). "While our data do not provide direct functional validation, this hypothesis is supported by prior studies showing that LAMA3 contributes to ECM remodeling and tumor invasiveness." (PMID 41264049, 2025). "Therefore, we used publicly available spatial transcriptomic (ST) data to interrogate sub-localizations of fDEGs in tumor core (TC), and leading edge (LE) of oral SCC (external dataset GSE208253), as exemplified for ITGB4, LAMA3, LAMB3, and LAMC2." (PMID 40121428, 2025). "Previous studies have indicated that LAMA3 could influence perineural invasion (PNI) by regulating extracellular matrix (ECM) composition and affecting tumor cell adhesion and migration." (PMID 41264049, 2025). "The predominant predicted tumor-to-microglia interactions in this model were driven by tumor junctional adhesion molecule (JAM) and extracellular matrix (ECM) ligands, such as collagens (e.g., COL4A2, COL6A3) and laminins (e.g., LAMA3, LAMC1)." (PMID 39372744, 2024). "Tumor tissues from patients with PDAC exhibiting liver metastasis showed higher LAMA3 expression than those without liver metastasis." (PMID 38452390, 2024). "The construction of the protein–protein interaction network provided additional insight into the functional roles of the selected genes, pinpointing LAMC2, LAMA3, and VEGFC as central nodes that could play crucial roles in tumor development and progression." (PMID 39766765, 2024). "Among the genes positively co-expressed with LAMA3, LAMB3, and LAMC2, there are important proteins which may change cancer cell behaviour and cancer progression in different tumours." (PMID 37779898, 2023). "As changes in the laminin gene expression have been associated with changes to the immunophenotype of a tumour in different contexts, we also queried the LAMA3, LAMB3, and LAMC2 genes in the TIMER2.0 database to investigate their relationship with tumour-infiltrating lymphocytes." (PMID 37779898, 2023). "Furthermore, we evaluated the possible link between the ECMGs and the tumor stage of PAAD, and 8 ECMGs (i.e. FN1, LAMA3, ITGB6, ITGB4, ITGA2, LAMC2, COL11A1, LAMB3) were detected to be significantly associated with tumor stage." (PMID 36311789, 2022). "Similarly, laminins were predominantly downregulated across tumour sample groups among which LAMA2 and LAMA3 were downregulated across all sample groups." (PMID 36220861, 2022). "LAMA3 is not a known tumor suppressor but SERPINB5, also known as maspin, has well-established tumor suppressor activity in breast cancer." (PMID 34680217, 2021). "Tumours that were mutant for Lama3 had areas in which the protein was absent from the basement membrane, consistent with a loss of function mutation, leading to multifocal breaks of the epithelial-mesenchymal boundary." (PMID 33168804, 2020).
tumor (continued). "In the expression level difference analysis, LAMA3 mRNA expression in PDAC non-tumor tissues in GSE102238 was lower when compared with tumor tissues from paired patients whose histopathology confirmed various extents of neurological invasion." (PMID 31182680, 2019). "Uncoupled regulation, namely induction of the LAMC2 but not the LAMA3 gene in response to signals derived from the tumor stroma at the invasive front of tumors is an important issue in tumor biology." (PMID 18664273, 2008). "Finally, dynamic changes in LAMA3 expression may reflect alterations in the tumor microenvironment, offering insights into the mechanisms of PDAC progression and tumor–nerve interactions." (PMID 41264049, 2025). "Corresponding to our investigation, another study observed the low expression of LAMA3 in 20 BC cell lines, which might be related to tumour metastasis, but there was no information for sEV LAMA3 in BC." (PMID 37895140, 2023). "Notably, we found p-EMT tumor cells (p-EMT sub-cluster) that highly expressed CDH1 (E-cadherin), keratin KRT14/16/17, TP63 (Tumor protein p63), and basement membrane ECM glycoprotein- Laminin family (LAMC2, LAMB3, LAMA3...)." (PMID 35742914, 2022). "Indeed, the tumor cores (L and LB) were found to express numerous pEMT genes at significantly greater levels than the TME, including the laminins (LAMC1, LAMC2, LAMA3), integrins (ITGA2, ITGB1, ITGAV), and inflammatory and neutrophil-attracting chemokines (CXCL8, CXCL1)." (PMID 36216799, 2022). "Genes related to cancer pathways were downregulated upon atezolizumab treatment, including angiogenic factors for tumor vascularization (TNK1, AREG and KDR), proto-oncogenes (RET and MET) and tumor cell survival/migration/invasion (CDH1, RARA, WNK2, WNT4A, WNT9A, TGFB2, EGF, and LAMA3)." (PMID 32616706, 2020). "However, both CD36 and LAMA3 are involved in ECM-receptor interaction pathways and if their functions were somehow disrupted, this could provide a mechanism for tumor spread." (PMID 32954225, 2020). "Our data would suggest that LAMA3 induction in HNSCC tumours is influenced by hypoxia but the lack of expression seen in our HNSCC cell lines implies that expression may also be dependant upon other factors found in tissues but not in cell culture." (PMID 19936049, 2009). "Although SCC tumor cells are known to produce laminin-332 proteins, the expression levels of all laminin-332 genes (Lama3, Lamb3, and Lamc2) were similar between TGF-β-responding and nonresponding tumor cells in vivo." (PMID 31792062, 2019). "In addition, all detected laminins were down-regulated in tumour samples compared to matched non-tumour samples, from 1.8-fold for laminin α2 chain (LAMA2) to 18.6-fold for laminin α3 chain (LAMA3)." (PMID 37397358, 2023). "In addition, although LAMA3 and E2F7 did not exhibit direct interactions with proteins involved in resistance to EGFR-TKIs, these two proteins were also connected to many proteins related to tumour progression." (PMID 31703415, 2019).